HSP90AA1 (heat shock protein 90 alpha family class A member 1)
Diseases named in the same sentence as HSP90AA1 in open-access papers (continued):
Sharing a sentence is not in itself a finding about the gene and the disease.
Parkinson disease (3 papers, 2013 to 2022). A progressive degenerative disorder of the central nervous system characterized by loss of dopamine producing neurons in the substantia nigra and the presence of Lewy bodies in the substantia nigra and locus coeruleus. "Besides being major contributors of neurodegeneration process, APP, CREB1, HSP90AA1, MAPT and PTEN have varying degree of interactions with many known Parkinson's disease genes (see CSPNW)." (PMID 24688734, 2013).
renal fibrosis (3 papers, 2022 to 2024). A final common manifestation of a wide variety of chronic kidney diseases characterized by glomerulosclerosis and tubulointerstitial fibrosis. "The active ingredient PTGS2 acts on HSP90AA1 to inhibit renal fibrosis through the AGE-RAGE signaling pathway." (PMID 39974825, 2024). "Through PPI network and molecular docking module analyses, CASP3, MMP9, ANXA5, and HSP90AA1 were identified as major pivotal gene targets in renal fibrosis." (PMID 37179298, 2023). "Therefore, the core genes CASP3, ANXA5, MMP9, and HSP90AA1 may play key roles in the inhibition of the occurrence and development of renal fibrosis." (PMID 37179298, 2023). "Network pharmacology analysis and experimental results suggest that diosmin ameliorates renal fibrosis by decreasing the expression of CASP3, ANXA5, MMP9, and HSP90AA1." (PMID 37179298, 2023). "Network pharmacology analysis and molecular docking technology were used to explore the potential mechanism of action of diosmin against renal fibrosis, and the key therapeutic targets of diosmin were identified as CASP3, MMP9, ANXA5, and HSP90AA1." (PMID 37179298, 2023). "The results suggested that 17 core compounds such as quercetin, kaempferol, luteolin, naringenin, and 23 core targets such as NCOA2, HSP90AA1, and PTGS1 might play an important role in JPYSF-treated renal fibrosis." (PMID 35656312, 2022).
acute myeloid leukemia (2 papers, 2019 to 2023). Acute myeloid leukemia (AML) is a group of neoplasms arising from precursor cells committed to the myeloid cell-line differentiation. "Exceptionally, SCAND2 and MZF1(ZSCAN6) gene expression was higher in acute myeloid leukemia (LAML), while the expression levels of HSP90AA1 and HSP90AB1 genes were lower, compared with paired normal tissues." (PMID 36982267, 2023).
age-related hearing loss (2 papers, 2023 to 2025). "For instance, in age-related hearing loss, the upregulation of heat shock protein 90AA1 (Hsp90AA1) has been reported to mitigate endoplasmic reticulum stress damage in SV cells." (PMID 39900910, 2025). "Whether any diagnostic or targeted intervention strategies for presbycusis can be developed based on HSP90AA1 requires further investigation." (PMID 36933008, 2023).
alcoholic fatty liver disease (2 papers, 2019 to 2024). Lipid infiltration of the hepatic parenchymal cells that is due to alcohol abuse. "The expression of HSP90AA1 was reported to be considerably decreased in the liver of patients with alcoholic fatty liver disease." (PMID 38751599, 2024). "A significant reduction in HSP90AA1 mRNA level in human liver is reported for alcoholic fatty liver disease (AFLD) patients in comparison with normal samples." (PMID 32099613, 2019).
Anxiety (2 papers, 2012 to 2025). Intense feelings of nervousness, tension, or panic often arise in response to interpersonal stresses. "Our laboratory has reported that long-term GR over-expression in mice show increased level of HSP90AA1 gene expression as well as altered emotionality (i.e., increased anxiety-like behavior) and increased psychomotor sensitization to cocaine." (PMID 22860061, 2012).
asthma (2 papers, 2024 to 2025).
bladder cancer (2 papers, 2016 to 2025). "Furthermore, pharmacogenomic screening identified several potential small-molecule inhibitors—alvespimycin, tanespimycin, and retaspimycin—that selectively target HSP90AA1 and may hold promise in sensitizing bladder cancer to immunotherapy." (PMID 41009692, 2025). "Among the differentially expressed genes, HSP90AA1 emerged as uniquely upregulated in both high-ICD score tumors and in bladder cancer tissues compared to normal controls." (PMID 41009692, 2025). "The smoking-related protein HSP90AA1 and DNA methylation of ECT2 mediate the progression from stage 1 bladder cancer cells to metastasis in stage 4 bladder cancer." (PMID 27034531, 2016).
Cirrhosis (2 papers, 2022 to 2024). A chronic disorder of the liver in which liver tissue becomes scarred and is partially replaced by regenerative nodules and fibrotic tissue resulting in loss of liver function. "HSP90AA1, a molecular chaperone involved in protein folding and stabilization, is potentially implicated in alcoholic hepatitis and cirrhosis." (PMID 38633610, 2024).
colorectal adenocarcinoma (2 papers, 2021). The most common type of colorectal carcinoma. "We quantified (RTqPCR) HSPA1 and HSP90AA1 expression in 50 polyp-normal pairs in relation to polyp malignancy potential and examined the effect of piroxicam, meloxicam and five novel analogues on HSPA1 and HSP90AA1 expression (mRNA/protein) in colorectal adenocarcinoma lines." (PMID 34827586, 2021).
Colorectal Polyps (2 papers, 2021 to 2024). "Here, we showed that both HSPA1 and HSP90AA1 transcripts are upregulated, to the same degree, in colorectal polyps as compared to polyp-adjacent tissue." (PMID 34827586, 2021). "HSPA1 and HSP90AA1 are upregulated in colorectal polyps reflecting their potential for malignancy." (PMID 34827586, 2021). "Heat shock proteins HSPA1/Hsp70α and HSP90AA1/Hsp90α are crucial for cancer growth but their expression pattern in colorectal polyps or whether they can be modulated by oxicams is unknown." (PMID 34827586, 2021).
dementia (2 papers, 2017 to 2022). Loss of intellectual abilities interfering with an individual's social and occupational functions. "HSP90AA1, involved in heat shock response (and its master regulator, i.e., HSF1), and EGFR are most important genes in pathology of dementia apart from KRs, given their presence as KRs as well as hubs in RN." (PMID 35327643, 2022).
fibromyalgia (2 papers, 2020 to 2023). A chronic disorder of unknown etiology characterized by pain, stiffness, and tenderness in the muscles of neck, shoulders, back, hips, arms, and legs. "Upregulation of the HSP90AA1 gene was observed in patients with fibromyalgia, and pharmacological inhibition of heat shock protein 90 (HSP90; encoded by HSP90AA1) was shown to alleviate monoarthritis-induced pain." (PMID 33343676, 2020).
glaucoma (2 papers, 2019 to 2025). Increased pressure in the eyeball due to obstruction of the outflow of aqueous humor. "On the contrary, the proteins HSP90AA1, HSPE1 and ERP29 are mainly functional as molecular chaperone complexes essential for the maintenance of the protein folding and protein trafficking, during cellular stress responses and are a hallmark for various neurodegenerative diseases, including glaucoma." (PMID 31443184, 2019).
heart failure (2 papers, 2011 to 2025). Inability of the heart to pump blood at an adequate rate to meet tissue metabolic requirements. "By using Cytoscape software (Version: 3.10.2) in conjunction with MCC algorithms of the CytoHubba plugin, we identified the top 5 hub genes within the network (IL1B, NFKB1, MAP2K1, PRKACA, and HSP90AA1), suggesting that these genes are potential targets for EMPA and MET in heart failure therapy." (PMID 40364820, 2025). "These genes included: carbonic anhydrase 3 (Ca3), an enzyme known to contribute to cardiac hypertrophy and heart failure when expressed in the heart; haptoglobin (Hp), a biomarker of inflammation and cardiovascular disease (CVD); and heat shock protein 90 (Hsp90aa1)." (PMID 21338512, 2011).
idiopathic pulmonary fibrosis (2 papers, 2022 to 2024). Idiopathic pulmonary fibrosis (IPF) is a nonneoplastic pulmonary disease that is characterized by the formation of scar tissue within the lungs in the absence of any known cause. "Additionally, Hsp90aa1 was significantly elevated in the lung tissues of an idiopathic pulmonary fibrosis rat model and is considered a novel system biomarker." (PMID 39220589, 2024). "By analyzing the target interaction network VCAM1,RELA,CDK2,JUN,CDK1,HSP90AA1,NOS2, SOD1,CASP3,AHSA1, PTGER3 are at the core of the network, which can be regarded as the key targets of Astragalus polysaccharides in treating pulmonary fibrosis." (PMID 35370663, 2022).
influenza (2 papers, 2022 to 2025). An acute viral infection of the respiratory tract, occurring in isolated cases, in epidemics, or in pandemics; it is caused by serologically different strains of viruses (influenzaviruses) designated A, B, and C, has a 3-day incubation period, and usually lasts for 3 to 10 days. "Additionally, HSP90AA1 stabilizes the PCBP1-AS1-encoded small protein (PESP), a recently discovered protein, overexpression of which regulates autophagy and enhances influenza replication." (PMID 40136667, 2025). "Moreover, HSP90AA1 is one of the binding proteins for influenza; thus, the use of HSP90AA1 targeting antibody could reduce viral entry, prevent the induction of autophagy, and suppress viral replication." (PMID 40136667, 2025). "Due to the interaction of HSP90AA1 with PB2, a subunit of IAV polymerase complex, the expression of NP protein increased the expression of HSP90AA1 and the binding of HSP90AA1 to PB2 to support influenza vRNA synthesis at early time points of infection." (PMID 34967267, 2022).
ischemic stroke (2 papers, 2022). A stroke disorder caused by obstruction of blood flow to the brain, due to thrombotic (local blood clot formation) or embolic (due to a blood clot or other material traveling from another site) event. "Notably, MAPK3, MAPK1, HSP90AA1, STAT3, PIK3R1, PIK3CA, and AKT1 were the main target proteins involved in the pathogenesis of ischemic stroke with Qi deficiency and blood stasis syndrome." (PMID 35401166, 2022). "After filtering out the common targets of FIB and Ischemic Strokes, 31 targets were screened for constructing the PPI network, and the top four core targets (CASP3, PTGS2, JUN, and HSP90AA1) were finally determined." (PMID 36467049, 2022). "CASP3, PTGS2, JUN, SLC6A4, and HSP90AA1 rank the top five in terms of degree value, indicating that these targets may be the key targets for FIB to treat ischemic strokes." (PMID 36467049, 2022).
lymph node metastasis (2 papers, 2021 to 2022). "Further statistical analysis revealed that the mRNA expression of AHA1, but neither Hsp90aa1 nor Hsp90ab1, is significantly correlated with the clinicopathological characteristics such as TNM stage (p = 0.035), lymph node metastasis (p = 0.012), and metastasis (p = 0.0003)." (PMID 34620942, 2021).
myopia (2 papers, 2022 to 2023). "The downregulation of Hsp90aa1 after atropine treatment may reduce HIF1α, thereby slowing down myopia progression." (PMID 35153787, 2022). "The 6 important intersectional targets of DZP for myopia treatment were STAT3, PIK3CA, PIK3R1, MAPK1, MAPK3, and HSP90AA1." (PMID 37747014, 2023).
nasopharyngeal carcinoma (2 papers, 2022 to 2024). A carcinoma arising from the nasopharyngeal epithelium. "Two core networks were generated by hub gene screening using the MCODE plugin of Cytoscape, and AKT1, CTNNB1, HSP90AA1, ESR1, CCND1, and EGFR were identified as key hub proteins, which may play an important role in the efficacy of icaritin in the treatment of nasopharyngeal carcinoma." (PMID 36467051, 2022).
osteoarthritis (2 papers, 2023 to 2024). A noninflammatory degenerative joint disease occurring chiefly in older persons, characterized by degeneration of the articular cartilage, hypertrophy of bone at the margins and changes in the synovial membrane. "Hsp90aa1 is downregulated in the blood and human osteoarthritic cartilage and is negatively associated with the risk of osteoarthritis." (PMID 39220589, 2024).
Salmonella Infections (2 papers, 2024). Infections with bacteria of the genus SALMONELLA. "Additionally, KEGG pathway analysis revealed significant enrichment in various signaling pathways, such as porphyrin metabolism, NOD-like receptor signaling pathway, Salmonella infection, ferroptosis, Notch signaling pathway, and herpes simplex virus 1 infection, involving hsp90aa1 and nfkbia." (PMID 39769404, 2024).
Tauopathies (2 papers, 2023). "A DisGeNET analysis showed Tauopathies as one of the top related diseases associated with HSP90AA1." (PMID 36766730, 2023).
thrombosis (2 papers, 2022 to 2025). "In summary, our study has revealed several crucial genes, including FOS, ICAM1, CASP3, and HSP90AA1, which likely play pivotal roles in the therapeutic effects of herbal medicine against venous thrombosis." (PMID 41327671, 2025).
ulcerative colitis (2 papers, 2024 to 2025). An inflammatory bowel disease involving the mucosal surface of the large intestine and rectum. "It is important to highlight that while this study has identified targets associated with ulcerative colitis (UC), such as TNF, ESR1, and HSP90AA1, the fundamental pathology of UC is driven by more specific factors and biomarkers." (PMID 40895135, 2025). "Previous studies have shown that inhibiting HSP90AA1 induces autophagy, thereby improving ulcerative colitis." (PMID 39664055, 2024).
vitiligo (2 papers, 2021 to 2023). Generalized well circumscribed patches of leukoderma that are generally distributed over symmetric body locations and is due to autoimmune destruction of melanocytes. "The hub genes of vitiligo melanocytes include CDK1, HSP90AA1, AKT1, BCL2L1, HDAC2, HELLS, and KIF23." (PMID 33790887, 2021).
acute respiratory distress syndrome (1 paper, 2022). Progressive and life-threatening pulmonary distress in the absence of an underlying pulmonary condition, usually following major trauma or surgery.
atrial fibrillation (1 paper, 2025). A disorder characterized by an electrocardiographic finding of a supraventricular arrhythmia characterized by the replacement of consistent P waves by rapid oscillations or fibrillatory waves that vary in size, shape and timing and are accompanied by an irregular ventricular response. "HSP90AA1 played an important role in atrial fibrillation by regulating lipid metabolism and biosynthesis." (PMID 40137123, 2025).
brain tumour (1 paper, 2024). "Of note, ANXA1, ANXA2, GNAS, HSP90AA1, HSP90AB1 and PSMD2, were highly abundant in EVs captured from GBM neurosurgical aspirates and in Pre-OP GBM uEVs here, implicating a potential brain tumour diagnostic utility for TRiC subunits and their interacting partners." (PMID 38212481, 2024).
celiac disease (1 paper, 2016). An autoimmune genetic disorder with an unknown pattern of inheritance that primarily affects the digestive tract. "The expression changes of HSP90AA1 in celiac disease is poorly documented, but in cancer research the 90-kDa heat shock protein HSP90AA1 is critical for the stability of several proteins that are important for tumor progression and introduced as a promising target for cancer therapy." (PMID 27895852, 2016). "HSP90AA1, MKKS, EZR, HSPA14, APOB and CAD are proteins that involved in protein networks of celiac disease and have been determined as seeds." (PMID 27895852, 2016).
cholestasis (1 paper, 2023). Impairment of the bile flow caused by obstruction within the liver, or outside the liver in the bile duct system. "Among them, HSP90AA1, TLR4, MMP2, APP, and NFKB1 were the crucial targets of FTA in the treatment of cholestasis." (PMID 37432229, 2023).
clear cell renal cell carcinoma (1 paper, 2026). "However, the role of HSP90AA1 in clear cell renal cell carcinoma (ccRCC) remains unclear." (PMID 41507145, 2026).
co-infection (1 paper, 2025). "Therefore, SRC and EGFR may serve as key targets for probenecid in treating SARS-CoV-2/RSV co-infection, while HSP90AA1 may play a lesser role." (PMID 40371107, 2025). "Subsequently, we obtained the top 16 hub targets of probenecid for SARS-CoV-2/RSV co-infection, namely, AKT1, ALB, EGFR, CASP3, CTNNB1, SRC, HSP90AA1, and so on." (PMID 40371107, 2025).
colorectal tumor (1 paper, 2022). "We note that four genes (SAT1, MT1E, HSP90AA1, and HNRNPH1) from a colorectal tumor tissue have interactions with HIV-1 proteins." (PMID 36290397, 2022).
Constipation (1 paper, 2022). Infrequent or difficult evacuation of feces. "Furthermore, the network pharmacology analysis showed that Akt1, Stat3, Mapk8, Hsp90aa1, Cat, Alb, Icam1, Sod2, and Gsk3b can be regarded as the core anti-constipation targets." (PMID 35408632, 2022).
delirium (1 paper, 2023). A disorder characterized by confusion; inattentiveness; disorientation; illusions; hallucinations; agitation; and in some instances autonomic nervous system overactivity. "The HSP90AA1 gene-encoded protein’s expression is associated with the inflammatory protein interleukins (IL) and the regulatory role in neurodevelopment, indicating a core connection with cognitive dysfunction and delirium." (PMID 37993790, 2023).
enteritis (1 paper, 2023). Inflammation of the small intestine. "The four main active compounds of MCE involved in the treatment of enteritis are SAN, CHE, PRO, and ALL, and the five core targets are HSP90AA1, MAPK1, HRAS, JAK2, and AKT1." (PMID 37200837, 2023).
esophageal cancer (1 paper, 2021). A primary or metastatic malignant neoplasm involving the esophagus. "Furthermore, treatment of immunodeficient mice bearing esophageal cancer xenografts (TE1 cell-derived) with alvespimycin hydrochloride (AH, an HSP90AA1 inhibitor) or ML-030 (a PDE4B inhibitor) remarkably suppressed tumor growth." (PMID 34294701, 2021).
Ewing sarcoma (1 paper, 2024). A small round cell tumor that lacks morphologic, immunohistochemical, and electron microscopic evidence of neuroectodermal differentiation. "Of the priority candidates, 6 were found with enriched dependency in Ewing Sarcoma cell lines (AKT1, BARD1, HSP90AA1, NCOA1, SETDB1, SMAD4)." (PMID 38177639, 2024).
Fanconi anemia (1 paper, 2019). Fanconi anemia (FA) is a hereditary DNA repair disorder characterized by progressive pancytopenia with bone marrow failure, variable congenital malformations and predisposition to develop hematological or solid tumors. "The power of the protein-processing machinery to operate as a modifier of disease outcomes has been shown recently by the demonstration that the activity of HSP90 (also known as HSP90AA1), the cytosolic paralog of GRP94, determined the severity of the cancer predisposition syndrome Fanconi anemia." (PMID 30733237, 2019).
gastrointestinal stromal tumor (1 paper, 2014). "Our previous study demonstrated NVP-AUY922, a HSP90AA1 inhibitor, could enhance mutant KIT degradation in gastrointestinal stromal tumor (GIST) cells through both proteasome- and autophagy-mediated pathways." (PMID 25375091, 2014).
gestational trophoblastic neoplasia (1 paper, 2021). "The mutation frequency of HSP90AA1 in gestational trophoblastic neoplasia was 18.2%." (PMID 34712697, 2021).